MMP9 (matrix metallopeptidase 9)
Diseases named in the same sentence as MMP9 in open-access papers (continued):
Sharing a sentence is not in itself a finding about the gene and the disease.
tumor (continued). "We have demonstrated a significant association between serum MMP9 concentration and the presence of neoplasia and this study supports previous work, which reported that patients referred with suspected neoplasia had significantly elevated MMP9 levels." (PMID 22433968, 2012). "High expression of tumour and stromal MMP-9 were significantly associated with positive lymph node status (P < 0.01)." (PMID 23107277, 2012). "The association between elevated MMP-9 immunoexpression and improved prognosis was evident only in Dukes’ B tumours, but it was such a strong prognostic factor that the association was significant in analysis of the whole cohort (p = 0.018)." (PMID 23216739, 2012). "Its expression in tumor cells or tissues is associated with MMP9 and with another matrix metalloproteinase, TIMP1." (PMID 22570691, 2012). "These multinucleate giant cells express matrix metalloproteinase-9 (MMP-9) which is responsible for the accelerated breakdown of the extracellular matrix associated with tumour invasion and metastases." (PMID 29147281, 2012). "It has been reported that emodin can inhibit tumor-associated angiogenesis through suppressing MMP-9 expression." (PMID 22876305, 2012). "Stromal expression of MMP-9 inversely associates with liver metastasis and tumour infiltration in CRC." (PMID 23216739, 2012). "MMP-9 and IL-8 expression levels increased together with tumor invasiveness, suggesting that they are probably associated with a worse outcome in BC." (PMID 22695075, 2012). "Matrix metalloproteinase 9 (MMP-9) has been associated with tumor cell invasion and metastasis in many human cancers, including BCa." (PMID 22559832, 2012). "Crude median MMP9 concentration differed between diagnostic groups, with higher MMP9 levels observed in the neoplasia group than the non-neoplasia group." (PMID 22433968, 2012). "ZOL decreased macrophage infiltration into the tumour stroma associated with significantly decreased levels of serum pro-MMP-9 and VEGF in all groups." (PMID 22005011, 2011). "Overexpression of MMP2 and MMP9 has been frequently detected in solid tumors and associated with tumor invasion and metastasis, including HCC." (PMID 21760911, 2011). "MMP9 is a Zn2+ dependent endopeptidase that mediates the degradation of extracellular matrix protein, and is associated with tumor invasion and metastasis." (PMID 20534121, 2010). "Further, inhibition of MMP-9 expression caused SPARC-mediated inhibition of angiogenesis and tumour growth as MMP-9 rescued SPARC-mediated anti-angiogenic effect in vitro and tumour growth inhibition in vivo." (PMID 20087345, 2010). "Genes, such as vascular endothelial growth factor (VEGF) and matrix metalloproteinase-9 (MMP9), have been reported to be linked to tumor metastasis, and NF-κB binding sites have been identified in their promoters." (PMID 20716363, 2010). "Elevated serum levels of MMP-9 are associated with tumour invasion and metastatic spread in a variety of malignancies." (PMID 19904265, 2009). "Concerning gastric cancer, it has been found that the T allele of the −1562 C/T polymorphism of MMP9 gene is associated with an invasive phenotype of this tumor and with a higher frequency of lymph node metastasis." (PMID 20037727, 2009). "Preclinical studies have demonstrated that MMP9 plays an important role in tumor-induced angiogenesis as well, with tumor-associated inflammatory and stromal cells being the main source of the proteinase." (PMID 20066159, 2009). "In fact, MMP-9 producing bone marrow derived cells have been implicated in both tumor angiogenesis and vasculogenesis." (PMID 19545375, 2009). "In oncology, the carrying of the T allele of the −1562 C/T MMP9 gene polymorphism is related to an increased risk for some kinds of cancer, more severe progression of tumor growth, and higher dynamics of metastases." (PMID 20037727, 2009).
tumor (continued). "Once in the tumor, E. coli for instance altered the tumor microenvironment in murine breast tumors by vascular remodeling, focal concentration of tumor associated macrophages and focal expression of MMP-9 and TNF-α around bacterial colonies." (PMID 19693266, 2009). "Multivariate logistic regression analyses will determine the independent factors (patient and disease related, MMP9) associated with the prediction of neoplasia." (PMID 19175925, 2009). "In castration-resistant tumours, there is an increase in angiogenesis that is associated with an increase in MMP-9." (PMID 18182993, 2008). "For example, tumor cells and tumor-associated macrophages are known to secrete matrix metalloproteinases, such as MMP-9 and MMP-2." (PMID 18042290, 2007). "The gelatinases, MMP-2 and MMP-9, have been particularly implicated in tumour invasion and metastasis formation." (PMID 17912241, 2007). "Previous studies have implicated other MMPs (i.e. MMP-2 and MMP-9) in tumor cell invasion and progression, and that LPA triggers upregulation or activation of MMP-2." (PMID 17156449, 2006). "Smaller tumors were formed when FaDu tumor cells were co-injected with MT1-MMP deficient fibroblasts as compared either MMP-2 null (80% smaller) or MMP-9 null (80% smaller) or WT fibroblasts (92% smaller)." (PMID 16515711, 2006). "MMP9 has been associated with angiogenesis, tumour progression and metastasis as mediated through degradation of the extracellular matrix (ECM) and stimulation of hyperproliferation." (PMID 16001974, 2005). "Matrix metalloproteinase 2 and MMP9 activity was significantly enhanced in urine from patients with highly invasive tumours, and also found to be associated with high stage and grade of bladder tumours." (PMID 15083203, 2004). "Matrix metalloproteinase-7 (MMP-7) and matrix metalloproteinase-9 (MMP-9) have been reported to have close associations with tumour invasion and metastasis." (PMID 14647147, 2003). "Additionally, PIK3CA mutations enrich for MMP9+ macrophages that promote tumor angiogenesis through ANGPTL4 signaling." (PMID 41958669, 2026). "Additionally, elevated levels of MMP2 and MMP9 are associated with worse prognosis, greater lymph node dissemination and increased tumour aggressiveness." (PMID 40259907, 2025). "MMP-9 is associated with metastasis and tumor malignancy in various carcinomas." (PMID 41303321, 2025). "Functional verification via gene overexpression elucidated distinct mechanisms underlying the action of FF: ESR1 acts as a tumor suppressor by enhancing FF’s anti-proliferative effect; conversely, c-Jun and MMP9 exhibit pro-cancer characteristics by counteracting FF’s activity." (PMID 40630198, 2025). "Moreover, intravenous transfer of CD45+ EPCs from cachexic HCC mice to tumour‐free mice caused elevation of Mmp9 autoantibodies in the serum and marked production of autoantibodies against the lung, liver, intestine, salivary gland, pancreas and spleen." (PMID 40665793, 2025). "Moreover, the transfer of CD45+ EPCs from cachexic HCC mice intravenously to tumour‐free mice caused a decrease in thymocytes compared to mFbs, decreased the mFb/capFb ratio and decreased Mmp9, LtβR and Ccl19 expression in mFbs." (PMID 40665793, 2025). "MMP9, ranking among the top five anoikis-related genes in differentially expressed genes in metastatic ccRCC has been implicated in cancer invasion, metastasis and upregulation across various tumour types." (PMID 40830065, 2025). "Importantly, this was accompanied by reduced expression of MMP9, a matrix metalloproteinase closely associated with tumor invasion and metastasis." (PMID 41010517, 2025). "MMP-9 overexpression is closely linked to tumor angiogenesis and invasive metastatic behavior." (PMID 40284474, 2025). "MMP2 and MMP9 are invasion-associated gelatinases responsible for extracellular matrix degradation and subsequent tissue invasion, and they have been described with elevated expression in canine neoplasms." (PMID 40509054, 2025).
tumor (continued). "Similarly, high MMP-9 expression has been associated with advanced tumor stage and lymph node metastasis in BC." (PMID 41303420, 2025). "Furthermore, MMP-9 also modulates tumor-associated inflammation through cytokines and their receptors." (PMID 40141020, 2025). "Considering that MMP9, E-cadherin, and Vimentin are linked to tumour invasion and metastasis — with Ki-67 serving as an indicator of cell proliferation — we verified their expressions in the pL-NC-LM3 and pL-sh-AC026412.33-LM3 groups via IHC and qRT-PCR analyses." (PMID 40790550, 2025). "Clinically, elevated tumor MMP-9 associates with poorer outcomes in early-stage disease, aligning with the concern that tamoxifen-selected phenotypes with higher MMP-9 activity could contribute to adverse biology in a subset of patients." (PMID 41304763, 2025). "Multiple studies implicated MMP-9 in the invasion and migration of tumor cells." (PMID 41154699, 2025). "Additionally, the activity of MMP9 in stroma remodeling suggests an association with more aggressive tumor phenotypes." (PMID 41263591, 2025). "In vivo experiments demonstrate that suppressing HIF-1α protein expression reduces the growth rate of subcutaneously formed tumors and decreases the expression levels of proteins associated with the P-PI3K/P-AKT, SOX2/OCT4, and MMP2/MMP9 pathways within the tumor." (PMID 39781344, 2025). "Similarly, MMP-9, which contributes to the extracellular matrix's breakdown, is linked to tumour invasion and metastasis and is frequently detected at high levels in OSCC." (PMID 40027232, 2025). "Additionally, through IL-17 overexpression, owing to MMP-9 expression and tumor cell invasiveness, IL-17 gene polymorphism exacerbates LC risk." (PMID 41179937, 2025). "Furthermore, MMP9 has been implicated in promoting tumor cell infiltration and metastasis by degrading type IV collagen and degraded collagen molecules." (PMID 41263591, 2025). "These elevated levels are associated with poorer OS, suggesting that MMP-9 levels may reflect the tumor’s invasive capacity and could serve as a prognostic marker." (PMID 41573658, 2025). "The reduction of KRAS may suppress matrix metalloproteinase (MMP1), MMP3, and MMP9, which are recognized as proteins associated with tumor metastasis, through a mechanism dependent on IL-17 signaling." (PMID 40486048, 2025). "MMP-9 is also involved in remodeling the tumor microenvironment, which may enhance tumor invasion and progression, and is associated with a poor prognosis." (PMID 39684754, 2024). "Furthermore, IL-6, CXCR4, CXCL8, and MMP-9 indicate higher diagnostic utility based on the AUC than the well-established tumor markers, such as CEA and SCC-Ag in OC patients." (PMID 38673838, 2024). "Furthermore, IL-6, CXCR4, CXCL8, and MMP-9 indicate higher diagnostic utility based on the area under the ROC curve (AUC) than well-established OC tumor markers, whereas CLDN18.2 can be used in novel targeted therapies for OC patients." (PMID 38673838, 2024). "The amount of MMP-9 produced by the TANs is much higher compared with TAMs, which may indicate worse prognosis and higher risk of metastatic spread of the tumours." (PMID 38920685, 2024). "Tumor-associated Gr1+CD11b+ mouse MDSCs produce MMP-9 and release VEGF-A to promote angiogenesis." (PMID 38580870, 2024). "Tumor-associated macrophages (TAMs) that express MMP9 and APOE were also present in this cluster." (PMID 39639005, 2024). "S-III tumours exhibit more aggressive characteristics including the upregulation of proteins associated with a poor prognosis (such as TGFβ1, KRT19 and MMP9) and the activation of tumour-promotion pathways (such as TGFβ, HIF1, integrin and Rho GTPases pathways)." (PMID 39261716, 2024). "The expression of MMP-9 by immunosuppressive TAMs is associated with tumor aggressiveness." (PMID 38248804, 2024). "MMP9 is also expressed by tumor-associated macrophages and neutrophils, which may contribute to MMP9 expression in primary tumors and metastases." (PMID 38441970, 2024).
tumor (continued). "Thus, parasite-induced reduction in MMP-9 expression in tumor-associated macrophages resulted in the suppression of tumor angiogenesis." (PMID 39367471, 2024). "Notably, studies involving mice deficient in MMP2 or MMP9 have underscored their essential role in promoting colonization and tumor proliferation." (PMID 38939095, 2024). "The elevation of MMP9 was associated with tumor growth and metastasis promotion in some cancers." (PMID 38254761, 2024). "MMP9, a zinc-dependent metalloproteinase involved in the degradation of extracellular matrix proteins, is implicated in various physiological and pathological processes, including cell signaling, immune response modulation, and tumor metastasis." (PMID 39850756, 2024). "Furthermore, POLQ knockdown distinctly reduced the expression levels of MMP2 and MMP9, which were associated with tumor metastasis and invasion." (PMID 39520627, 2024). "In addition, decreased expression of vimentin, Twist, MMP-2 and MMP-9 is associated with inhibition of tumor growth, cell migration, invasion and cancer metastasis and increased sensitivity to chemotherapeutic agents." (PMID 38737746, 2024). "Additionally, Plasmodium-derived hemozoin that accumulated in tumor-associated macrophages inhibited IGF-1 signaling through the PI3-K and MAPK signaling pathways and thereby decreased the expression of MMP-9 in tumor-associated macrophages." (PMID 39367471, 2024). "In contrast, anti-MMP-9 treatment increased the expression of T-cell-associated stimulatory factors, which significantly enhanced T-cell-mediated cytotoxicity and thereby inhibited tumor progression." (PMID 37313408, 2023). "In 3D spheroids, BMSCs cause a marked downregulation of MMP-9 promoter activity in tumor cells." (PMID 36674806, 2023). "MMP2 and MMP9 overexpression is associated with higher tumor grades." (PMID 37239013, 2023). "Among these, MMP-2 and MMP-9 are highly associated with tumor dissemination and invasiveness." (PMID 37047801, 2023). "However, functional studies, including MMP-9 activity measurements, would be needed to explore the causal relationship between tumour progression and the MMP-9 level of serum sEVs." (PMID 36765669, 2023). "Cluster 9 is a small, distinct population of macrophages that not only expressed a high level of oxidative phosphorylation but also had an exclusively high level of MMP-9, secretion of which by TAMs has been associated with tumor progression and mesenchymal transition." (PMID 36757811, 2023). "Overall, our findings not only provide a novel mechanism of TANs associated LN metastasis of tumor cells via ETV4‐CXCL1/8‐CXCR2‐VEGFA/MMP9 pathway‐mediated lymphangiogenesis, but also point to potential targets for drug development against LN metastasis of BCa." (PMID 36670069, 2023). "Thus, lowered neutrophil counts and concomitants reduction in MMP-9-positive tumor tissue cells together with increased Granzyme B-positive tumor-associated cells, reflect the anti-cancer mechanisms of AAT augmentation therapy." (PMID 37532996, 2023). "In addition, the incomplete removal of the tumor, recurrent PA, and positive MMP-9 expression were confirmed as increased risk factors for recurrence of PA following surgery." (PMID 36831707, 2023). "The exact cause of the increased production of MMP-9 in tumor tissue is poorly understood to date." (PMID 36674806, 2023). "Some neutrophil populations, known as tumor-associated neutrophils (TANs), promote cancer cell growth, invasion, and angiogenesis by producing matrix metalloproteinase-9 (MMP9), vascular endothelial growth factor (VEGF), and hepatocyte growth factor (HGF) at primary and metastatic sites." (PMID 37644235, 2023). "In addition, matrix metalloprotease type-9 (MMP-9) generated by tumor-associated neutrophils (TANs) and macrophages in the TIME potentiate the effects of VEGF." (PMID 36874130, 2023).
tumor (continued). "In the case of some peripheral tumours, elevated MMP-9 levels in plasma were detected and associated with cancer development, invasion, and poorer survival; however, according to other research, MMP-9 in blood samples cannot be considered useful in estimating the invasive capacity of cancer." (PMID 36765669, 2023). "Moreover, MMP2 expression in CAFs and MMP9 expression in the tumour nest at the TSI was significantly associated with ENE + but not with TME activity-related features (TB, DR, and TILs)." (PMID 36765296, 2023). "Disease progression-related increase in MMP-9 and progressive loss of laminin-1 with increasing tumor grade may be involved in the progression from normal to hyperplastic and to low- and high-grade cancerous endometrium." (PMID 36945954, 2023). "MMP2 and MMP9 activation has been implicated in tumor invasion and metastasis in GC." (PMID 35705840, 2022). "Indeed, in a 3D Matrigel-based system, the interplay between the human macrophage U937 cell line and breast tumor cells caused, in U937, a significant upregulation of MMP1 and MMP9, both involved in tumor invasion via ECM degradation." (PMID 35205760, 2022). "MMP2 and MMP9 was highly associated with primary tumor status (T)." (PMID 35449123, 2022). "MMP-9 is secreted by leukocytes and is associated with various tumor cells' aberrant behavior." (PMID 35572966, 2022). "MMP2 and MMP-9 are associated with tumor invasion and metastasis, and the concentration of these biomarkers differs significantly in the saliva of healthy individuals, patients with premalignant diseases of the oral cavity, and OSCC patients, suggesting their diagnostic and prognostic role." (PMID 36412636, 2022). "G-MDSC could be differentiated into tumor-associated neutrophils, which immunosuppressive functions are mediated by metabolites (e.g. Arg-1, ROS, NO) and soluble regulatory factors IL-10, MMP-9, and VEGF7–9." (PMID 35589776, 2022). "Among them, MMP-2 and MMP-9 are the most distinctive MMPs characterized by a strong proteolytic activity in the extracellular matrix, which could be overexpressed in tumor cells and may be linked to risky metastasis and/or poor prognosis." (PMID 36230852, 2022). "MMP2 and MMP9 are gelatinases of matrix metalloproteinase family, which were initially associated with the invasive and metastatic properties of tumour cells, owing to their ability to degrade major protein components of the extracellular matrix and basement membranes." (PMID 36153370, 2022). "Matrix metalloproteinases (MMPs), mainly including MMP-2 and MMP-9, which are overexpressed in the tumor microenvironment, have long been closely implicated in tumor invasion and metastasis and can be applied as stimuli for the design of bio-responsive materials." (PMID 35845404, 2022). "MMP9 is a matricellular protein associated with extracellular matrix remodeling that regulates the activity of cell adhesion molecules and cytokines and promotes tumor progression." (PMID 36118887, 2022). "Both MMP-2 and MMP-9 are known to be associated with tumor metastasis and angiogenesis." (PMID 36483979, 2022). "Importantly, tumor-associated neutrophils were reported to have significantly more abundant MMP-9, readily available for rapid release, than tumor-associated macrophages." (PMID 35158807, 2022). "In principle, MMP9 is secreted by tumor-associated fibroblasts and cancer cells." (PMID 36361816, 2022). "In addition, N2 TANs in the TME are also associated with tumor angiogenesis by recruiting matrix metalloproteinase-9 (MMP-9)." (PMID 36384979, 2022). "Finally, to explore the involvement of MMP9 in angiogenic and invasive processes, we concomitantly analyzed the baseline plasma expression of five related factors implicated in the tumor microenvironment: MMP2, VEGFA, VEGFR2, CXCR4, and CXCL12." (PMID 34980260, 2022). "In addition, in colitis associated CRC, MMP-9 can prevent γH2AX reduced levels of genotoxicity, also plays a tumor suppressive role." (PMID 36246294, 2022).